MEG3 (maternally expressed 3)
Diseases named in the same sentence as MEG3 in open-access papers (continued):
Sharing a sentence is not in itself a finding about the gene and the disease.
tumor (continued). "MEG3 is a tumor-suppressive lncRNA that has recently been identified as potentially useful in the clinic in PTC." (PMID 41154428, 2025). "This suppression of MEG3 transcription underscores DNA methylation as a key contributor to placental toxicity, given MEG3’s typical functions in tumor suppression and placental health." (PMID 40566344, 2025). "LncRNA maternally expressed gene 3 (MEG3), which is present in the nucleus and cytoplasm, has a tumour-suppressive function across cancers, including colorectal, cervical, lung, gastric, ovarian, glioma, breast, liver, and osteosarcoma, among others." (PMID 41463281, 2025). "Highly regulated DEGs in the SPF DOWN cluster include genes that have been associated with tumour suppression and CRC (Meg3, Cwh43, Naprt), lipid metabolism and detoxification (Ces1f) and bactericidal/antimicrobial activity (Iapp)." (PMID 40890536, 2025). "MEG3 has been found to be downregulated in a wide range of neoplasms, including squamous cell carcinoma of the head and neck, neuroblastoma, glioma, meningioma, retinoblastoma, and thyroid cancer." (PMID 41141357, 2025). "Conversely, knockdown of MEG3 promotes tumor progression by upregulating PD-1/PD-L1 expression and shifting immunity toward a Th2-skewed response." (PMID 41186893, 2025). "In papillary renal cell carcinoma, MEG3 expression was downregulated in tumor tissues relative to that in adjacent normal tissues." (PMID 40242248, 2025). "MEG3 rs4081134 and rs7158663 binary logistic regression analysis based on tumor recurrence, hormonal activity, and invasiveness." (PMID 41141357, 2025). "GAS5’s broad impact on tumor suppression through miRNA regulation parallels MEG3’s function, though it targets different specific miRNAs, enhancing the collective miRNA regulatory spectrum in this cancer type." (PMID 40242248, 2025). "These preclinical results reinforce MEG3’s role as a tumor suppressor and highlight its potential as a promising therapeutic target." (PMID 40242248, 2025). "As a widely studied tumor suppressor-related lncRNA, lncRNA maternally expressed gene 3 (MEG3) has been confirmed to regulate cell apoptosis, proliferation, and other processes by targeting different miRNAs." (PMID 41156747, 2025). "Maternally expressed gene 3 (MEG3) is an lncRNA, which is maternally imprinted and serves as a tumor suppressor gene, found in chromosome 14q32.3." (PMID 40568293, 2025). "On the contrary, a lncRNA characterized by a tumor suppressor activity is MEG3 since its downregulation activates Wnt pathway through the regulation of miR-21/E-Cadherin axis leading to a mesenchymal phenotype." (PMID 40282449, 2025). "Beyond its well-known role as a tumor-suppressive lncRNA, mounting evidence indicates that MEG3 plays crucial regulatory roles in the occurrence and development of various diseases." (PMID 41156747, 2025). "Maternally expressed gene 3 (MEG3) is an imprinted, non-coding RNA gene originally identified as a tumor suppressor." (PMID 40765563, 2025). "Although the general function of MEG3 in tumor suppression is being gradually uncovered, its involvement in PitNET pathophysiology remains relatively unexplored." (PMID 41141357, 2025). "Maternally expressed 3 (MEG3) is a lncRNA, located on chromosome 14, and has been found to be dysregulated in BC cells, showing suppressed expression levels in tumour cells." (PMID 40863727, 2025). "Specifically, a substantial decrease of MEG3 expression was observed in tumor samples (p = 1.4e-41), with the lowest expression observed in metastatic samples (p = 2.7e-06)." (PMID 40548301, 2025).
tumor (continued). "For example, curcumin-treated OC cells showed overexpression of the tumor-suppressor lncRNA MEG3, both in OVCAR3 and SKOV3 cells as well as the sEVs derived from them." (PMID 39941838, 2025). "The restoration of MEG3 expression through demethylating agents has been proposed as a potential therapeutic strategy, focusing on the reactivation of its tumor-suppressing effects." (PMID 40362297, 2025). "In vivo, MEG3 overexpression in PC3 cells resulted in significantly reduced tumor weight and volume in mice, reinforcing its tumor-suppressive properties." (PMID 40242248, 2025). "Another tumor-suppressor lncRNA, MEG3, sequesters miR-376a, which promotes cell proliferation by targeting Krüppel-like factor 15 (KLF15) and Caspase-8." (PMID 39941838, 2025). "These activities align with MEG3’s, presenting a coordinated defense against key signaling pathways that promote tumor growth." (PMID 40242248, 2025). "Overexpression of MEG3 can lead to a significant reduction in tumor growth, decreased expression of PD-1/PD-L1s in macrophages, and enhanced Th1 response." (PMID 41186893, 2025). "MEG3 primarily functions by promoting apoptosis and by inhibiting proliferation, angiogenesis and metastasis, marking it as a universal tumor suppressor in these cancers." (PMID 40242248, 2025). "Upregulated lncRNA MEG3 exerts tumor-suppressive effects via suppression of cell proliferation, induction of apoptosis, learning and memory." (PMID 40928594, 2025). "Conversely, certain lncRNAs, such as MEG3, frequently exhibit a reduced expression in a variety of malignancies, which implies that they serve as tumor suppressors." (PMID 40671967, 2025). "MEG3 also has tumor suppressor activity, enhancing apoptosis and cellular sensitivity to treatments." (PMID 41150811, 2025). "Conversely, MEG3 is a tumor suppressor lncRNA that inhibits tumorigenesis by negatively regulating the PAM signaling pathway." (PMID 40041495, 2025). "MEG3, short for Maternally Expressed Gene 3, is a relatively well-known tumor-suppressive lncRNA, whose expression is often downregulated in HBV-HCC." (PMID 40625740, 2025). "Conversely, Maternal Expressed Gene 3 (MEG3) lncRNA has been demonstrated to function as a tumor suppressor in CCA." (PMID 39766138, 2024). "The abnormal expression of MEG3 can inhibit the proliferation, migration, and invasion of tumor cells and promote tumor cell apoptosis." (PMID 38281945, 2024). "Maternally expressed gene 3 (MEG3) is an imprinted long non-coding RNA (lncRNA) gene (locus 14q32.2) that is expressed maternally and functions as a tumor suppressor." (PMID 39795985, 2024). "Recent years, lncRNA MEG3 was discovered to be a tumor suppressor gene, which can be involved in angiogenesis and tumorigenesis." (PMID 38824534, 2024). "Our results demonstrate a novel mechanism by which lncRNA MEG3 can act as a tumor suppressor and regulate endothelial angiogenesis through the exosomal miR-421/HS2ST1 axis, which provides a potential therapeutic strategy for OSCC angiogenesis." (PMID 39062818, 2024). "We further confirmed the influence of MEG3 on tumor growth in vivo by orthotopic xenograft models and IHC assay." (PMID 38281945, 2024). "Some studies have suggested that MEG3 suppresses tumor cell proliferation and invasion by downregulating related proteins." (PMID 38827318, 2024). "Maternally expressed gene 3 (MEG3), a long non-coding RNA (lncRNA), has been reported to function as a tumor suppressor gene in various solid cancers." (PMID 39062818, 2024). "In human tumor samples, we found that the MEG3 gene was generally hypomethylated, except for the particular CGIs inside MEG3-DMR, with significant hypermethylation in cg15419911 and cg14245102 (CGI 18) and cg04291079 (CGI 78)." (PMID 38920632, 2024). "Consistently, the high levels of MEG3 were verified in GHPA tumor tissues with single mutant sites at Q227L and R201C (4.7-fold, p = 0.0004; 4.4-fold, p = 0.0033)." (PMID 38827318, 2024).
tumor (continued). "Intriguingly, MEG3 expression further increased in the 16 GHPA tumor tissues with mutant GNAS compared with the 28 wild-type tumors (p = 0.006)." (PMID 38827318, 2024). "The lncRNA maternally expressed gene 3 (MEG3) located on chromosome 14q32.3 is enacted as a tumor suppressor in multiple malignancies, including CRC14,15." (PMID 38704452, 2024). "In concordance with the global downregulation of the DLK1-DIO3 region previously reported, we observed a pronounced suppression of MEG3 expression in the tumor cell lines." (PMID 38920632, 2024). "The maternally expressed gene 3 (MEG3) protein, derived from the long non-coding RNA MEG3, is markedly downregulated in various tumor tissues and cell lines, impacting tumor progression." (PMID 39765842, 2024). "CNN1 (log2FC = −3.885), ARHGAP20 (log2FC = −3.312), and MEG3 (log2FC = −2.612) were downregulated, whereas miR-330 (log2FC = 0.431) was upregulated in tumor samples compared to normal samples." (PMID 38240701, 2024). "It has been reported that MEG3 levels are reduced in many human malignancies, and it functions as a tumor suppressor, by modulating common cell signal transduction pathways." (PMID 39049088, 2024). "In most tumor types, MEG3 acts as a tumor suppressor by directly interacting with miRNAs or acting as their molecular sponge." (PMID 39049088, 2024). "The sustained efficiency of MEG3 upregulation was verified by detecting the expression level of MEG3 in the xenograft tumor of each mouse via RT-qPCR." (PMID 38827318, 2024). "Intriguingly, serum MEG3 expression level was negatively correlated with tumor stage (r = − 0.224, P = 0.049), while there was a positive correlation between serum SIRT1 levels and the anatomical site (r = 0.28, P = 0.023)." (PMID 38704452, 2024). "MEG3, according to literature reports, is responsible for the inhibition of tumor growth and metastasis by modulating the miR-21/E-cadherin axis." (PMID 38601651, 2024). "Their findings demonstrated that these engineered exosomes (cRGD-Exo-MEG3) exhibited improved efficiency in targeting OS cells, enhancing anti-tumor effects in vitro and in vivo." (PMID 38203737, 2024). "Accordingly, MEG3 upregulation inhibited tumor cell invasion, and conversely, MEG3 downregulation increased tumor cell invasion." (PMID 38827318, 2024). "Overexpression of the lncRNA maternally expressed gene-3 (MEG3), also referred to as gene trap locus 2 (Gtl2), reduces neuronal activity and inhibits cell proliferation and tumor development." (PMID 38472261, 2024). "explored the mechanism underlying the tumor‐suppressive effect of ADH4 and discovered the MEG3/miR664a‐3p/ADH4 axis." (PMID 39540710, 2024). "Altered expression of maternally expressed 3 (MEG3), a tumor-suppressing lncRNA, was observed to enhance epithelial-to-mesenchymal transition (EMT) in several solid tumors." (PMID 38333212, 2024). "MEG3 increases the expression of programmed death-ligand-1 (PD-L1) which acts as a tumour suppressor, and its levels are downregulated in EC cells." (PMID 38893244, 2024). "Compared with those injected with vector control cells, mice injected with MEG3 knockdown cells showed larger tumor volumes and faster growth rates." (PMID 38281945, 2024). "The levels of MEG3 considerably increased in 44 GHPA tumor tissues compared with the 10 NFPA tumor tissues (p = 0.0003)." (PMID 38827318, 2024).
tumor (continued). "The combined treatment (5-Aza + trichostatin A) successfully restored MEG3 expression in all tumor cells, indicating that the gene is controlled by both methylation and histone alterations." (PMID 38920632, 2024). "MEG3 is another significant tumor-suppressing lncRNA that shows reduced expression in gastric and liver cancers." (PMID 39553554, 2024). "Mechanistically, MEG3 acted as tumor suppressor in CCA through polycomb repressive complex 1 and by targeting miR-361–5p/TRAF3 axis." (PMID 39766138, 2024). "Menin can also suppress pNET tumorigenesis by activating the transcription of the tumor-suppressive lncRNA MEG3." (PMID 39336822, 2024). "The levels of CD8+ T cells and FOXP3+ Tregs in the TME significantly affect the survival of tumor cells, suggesting that the high expression of MEG3 plays an important role in tumor immune escape." (PMID 39263534, 2024). "Studies have demonstrated that MEG3 negatively regulates the Wnt/β-catenin signaling pathway in tumor growth and invasion." (PMID 38827318, 2024). "Maternally expressed gene 3 (MEG3), a large non-coding RNA (lncRNA), was first identified as a tumor suppressor in the pituitary." (PMID 38827318, 2024). "Maternally expressed gene 3 (lncRNA MEG3) is one of these tumor suppressor lncRNAs that have received a lot of attention." (PMID 38294554, 2024). "Illustratively, the lncRNA MEG3 is a tumor suppressor transcript located on the 14q32.3 chromosome in humans and is frequently underexpressed in an array of malignancies." (PMID 38745221, 2024). "MEG3 expression was negatively correlated with DNMT1 and DNMT1 knockdown increased MEG3 expression and inhibited tumor growth in mice tumor model." (PMID 38277283, 2024). "We found that LncRNA MEG3 is a novel tumor suppressor, but its role in tumor occurrence and development is still unclear." (PMID 38281945, 2024). "The CAF Meg3 cluster exhibited an almost threefold increase in dKO tumours, and with NC Zeb2, this cluster was the most relatively enriched cell type." (PMID 37605008, 2023). "Further studies on the role of MEG3 on tumor cell apoptosis indicate that MEG3 sponges miR-23b-3p and restores the expression of FOXO4." (PMID 38204968, 2023). "It has been shown that the overexpression of MEG3 can induce apoptosis and regulates the cell cycle that arrests tumour cell growth." (PMID 38203731, 2023). "MEG3 is usually acts as a tumor‐suppressive lncRNA, which is downregulated in tumor tissues and cells." (PMID 36468944, 2023). "To further elucidate the tumor‐suppressive mechanism of MEG3, we predicted transcription factors of the intersecting genes, and confirmed the binding between MEG3 and transcription factor GATA3 in OSCC cells." (PMID 36468944, 2023). "Although there is a significant reverse correlation between tumour malignancy and MEG3 expression in previous reports, we found that MEG3 activity differs between different cell lines and is mostly correlated with the IDH1 mutation status." (PMID 37525401, 2023). "MEG3 was downregulated in the tumor tissues from human lung squamous cell carcinoma compared to those from adjacent normal lung tissues." (PMID 36851033, 2023). "MEG3, the human ortholog of Gtl2, is downregulated in many forms of cancer and, therefore, is believed to function as a tumor suppressor." (PMID 38155837, 2023).
tumor (continued). "Maternally expressed gene 3 (MEG3) is another highly studied lncRNA shown to regulate cell proliferation and is considered a tumor suppressor." (PMID 36869839, 2023). "Grade 3 (p = 0.003) and Grade 4 (p = 0.0061) tumours showed a significantly increased level of MEG3 gene expression whereas Grade 1 and Grade 2 tumours showed the least amount of expression." (PMID 37525401, 2023). "MEG3 regulates cell proliferation, cell cycle, apoptosis, hypoxia, autophagy, and many other processes involved in tumor development." (PMID 36851033, 2023). "Among the related lncRNAs, MEG3 was confirmed to be lowly expressed in female-related tumors, and as a tumor suppressor to inhibit the malignant progression of cancer cells in vitro and in vivo." (PMID 37392565, 2023). "It was further reported that knockdown of MEG3 in fibroblasts was correlated with a decrease in key matrix metalloproteinase expression (i.e., MMP-1, MMP-9, and MMP-16), thereby providing evidence of a role for MEG3 in tumor neovascularization and metastasis." (PMID 37373059, 2023). "MEG3 overexpression has been shown to mitigate PCa cell proliferation and metastasis, induce apoptosis, and attenuate tumor development in mice." (PMID 38047026, 2023). "Functional assays demonstrated that miR-21-5p inhibitor suppressed cell colony formation and invasion abilities and counteracted MEG3-knockdown induced tumor-promoting effects in 95D and H1299 cells." (PMID 37308993, 2023). "In different solid tumors and in diverse tumor cell lines, MEG3 overexpression inhibits proliferation, hence it is used as a tumor suppressor gene." (PMID 37388937, 2023). "Our study illustrated that the representative PRAPi drug niraparib, restrained PCa cell proliferation, migration and invasion and delayed tumor growth in mice by regulating the MEG3/miR-181-5p/GATA6 pathway." (PMID 38047026, 2023). "The second biomarker included in our AML prognostic model, namely, MEG3, is a recently found lncRNA with tumor-suppressive function that is very critical at the onset and development of several cancers." (PMID 37388937, 2023). "Ectopic expression of MEG3 attenuated tumor EMT and invasion by influencing the expression of MMP7, E-cadherin, and survivin." (PMID 38204968, 2023). "During the gene therapy of OS, engineered exosomes modified by cyclic RGD peptide (cRGD-Exo-MEG3) demonstrated 2.5-fold tumor targeting ability and twofold antitumor effects in vivo compared with Exo-MEG3." (PMID 36944946, 2023). "For instance, MEG3 is a tumor suppressor in many cancers, while NLRP3 regulates inflammation and cell death, which play crucial roles in tumorigenesis." (PMID 37511974, 2023). "As such, the potentially inverse association between 14q32 miRNA expression and prognosis in our CLL subgroups is notable in that it would coincide with the tumour suppressor potential of the 14q32 miRNA and MEG3 lncRNA." (PMID 37169950, 2023). "It was concluded that the tumour suppressive effects of MEG3 were by sponging (binding and inactivating) miRNA-141 activity and expression, thereby preventing the microRNA from suppressing the expression of PDCD4." (PMID 35847932, 2022). "MEG3 has obvious tumor suppressor properties in ESCC tissue, and its expression is negatively correlated with lymph node metastasis and TNM staging." (PMID 35241975, 2022).